TLR4 (toll like receptor 4)
Diseases named in the same sentence as TLR4 in open-access papers (continued):
Sharing a sentence is not in itself a finding about the gene and the disease.
Salmonella Infections (continued). "Besides previous gene expression data, selection of this miRNA was supported by its biological implication during S. Typhimurium infection: TLR4 is the main pathogen recognition receptor, and it triggers the inflammatory signaling cascades in response to Salmonella infection." (PMID 35598011, 2022). "A network analysis identified an interaction between the Toll-like receptor pathway and Salmonella infection via TLR4 and TLR2, the NOD-like receptor pathway and Salmonella infection via GBP1, and the TNF signaling pathway and Salmonella infection via IRF1." (PMID 40005871, 2025). "However, TLR-4 might also respond to E. coli and Salmonella infection." (PMID 39457937, 2024). "The mRNA expression of TLR4 and TLR5 in the ileal mucosa was significantly upregulated by Salmonella infection compared to the CON group (P < 0.05)." (PMID 39533418, 2024). "The results revealed that Salmonella infection up-regulated all studied pro-inflammatory cytokines such as TNF-α, IL-8, IL-6 and TLR4, TLR5 signaling pathways, while decreasing the expression of TGF-β." (PMID 36556320, 2022). "Sensory neurons in the gut of mice release CGRP to defend against Salmonella infection, and neurogenic inflammation challenged with LPS can promote CGRP release via activation of Toll-like receptor 4 (TLR4) in sensory neurons." (PMID 35592257, 2022). "The TLR4, TLR15, TLR21, MD-2, ILs, IFNs, and iNOS have been reported as resistant genes against salmonella infections." (PMID 34512716, 2021). "In terms of functional aspect related to mROS, CRBNKD THP-1 cells exhibited resistance against Salmonella infection, strongly indicating the negative regulation of CRBN on bactericidal activity induced by TLR4 stimulation." (PMID 31620128, 2019). "The Salmonella infection upregulated LBP, CD14, TLR4, and LBP in the colon." (PMID 38003758, 2023). "TLR4 and TLR21 (which is functionally equivalent to mammalian TLR9) recognize and bind with their respective ligands LPS and Unmethylated (or 5′—C—phosphate—G—3′) DNA sequences are considered to be key players in immunity against Salmonella infection." (PMID 34446765, 2021). "Toll-like receptor (TLR) signaling pathways, especially the TLR4-MyD88-dependent pathway, and nucleotide-binding oligomerization domain (NOD)-like receptor (NLR) signaling pathways play an essential role in defense against Salmonella infection." (PMID 32075044, 2020). "Considered to the function of TLR2, TLR4, TLR7, TNF2, IL8, and IL18, it was revealed that the immune defense would been inhibited for REV infection through salmonella infection, NOD-like receptor, Toll-like receptor and MAPK-AP1 pathways." (PMID 29410628, 2018). "They concluded that as recognition of microorganisms by TLR-4 and activation of phagocytes by IFN-γ are crucial mechanisms for the defence against intracellular pathogens, their inhibition by anti-TNF leads to severe complication with Salmonella infections." (PMID 26425605, 2014). "Moreover, TLR2, TLR4, TLR7, and IL8 were enriched in Toll-like receptor pathway, IL8 and IL18 were enriched in the NOD-like receptor pathway, and TLR4, IL8, and IL18 were enriched in the salmonella infection pathway." (PMID 29410628, 2018).
fibrosis (49 papers, 2009 to 2026). the formation of excess fibrous connective tissue in an organ or tissue in a reparative or reactive process. "Meanwhile, TLR4 SNP leads to a T399I change caused a remarkably decreased risk for fibrosis development in patients with chronic liver injury." (PMID 32425800, 2020). "Fibrosis progression was independently associated with TLR4 expression (β=0." (PMID 29379592, 2017). "This was accompanied by increased dermal fibrosis in aged mice and a transcriptomic profile that indicates a key role for both TLR4 and TGFβ signaling." (PMID 42123714, 2026). "Peripheral monoterpenes display similar behaviour: α-pinene dampens hepatic TLR4/NF-κB signalling in Carbon tetrachloride (CCl4)-induced fibrosis, and tea tree-derived α-terpineol inhibits TLR4-triggered IL-1β and IL-6 production in human macrophages." (PMID 40872493, 2025). "Other mechanisms involved in EMT induction that leads to intestinal fibrosis include toll-like receptor 4 (TLR4) and succinate stimulation." (PMID 35370998, 2022). "JMJD2D contributes to hepatic fibrosis progression by promoting TLR4 transcription through H3K9me2/3 demethylation and then activates TLR4/NF-κB signaling in HSC." (PMID 35740507, 2022). "LPS/TLR4 and TLR2 signaling has been suggested to be involved in hepatic inflammation-fibrosis-carcinoma (IFC) sequence, which is linked to viral hepatitis." (PMID 36544761, 2022). "Another group showed that TLR4-deficient mice developed less tissue fibrosis, decreased polarization of Th17 responses, and decreased TGF-β in the bleomycin-induced fibrosis and the tight skin models." (PMID 30809542, 2019). "We examined the effect of TAK242, a small molecule TLR4 inhibitor, in preclinical fibrosis models and in SSc fibroblasts." (PMID 30405628, 2018). "An interesting observation was that HA/TLR2 and HA/TLR4 interactions alter sensitivity to lung inflammation and fibrosis upon lung injury." (PMID 28836991, 2017). "Paun and colleagues analyzed the effects of 18Gy (Gray) WTI on the development of pneumonitis or fibrosis in mice deficient for TLR2 (TLR2−/−), TLR4 (TLR4−/−), and TLR2/4 double knockout mice (TLR2−/−/TLR4−/−)." (PMID 28836991, 2017). "TLR4 signaling pathway also regulates myocardial fibrosis by inhibiting its target genes." (PMID 38455049, 2024). "However, this activation and induction of organ fibrosis require a primed cellular microenvironment, which can be induced by TLR4 activation, suggesting that TLR4‐dependent fibroblast activation is a key driver of persistent organ fibrosis." (PMID 34953031, 2022). "Thus, activation of TLR4 in HSCs has been suggested to be the main mediator of fibrosis and cirrhosis, by initiating collagen production." (PMID 36544761, 2022). "In addition to integrins, a recent study reported EDA-FN-dependent signaling through toll-like receptor 4 (TLR4) drove fibrosis in scleroderma." (PMID 33557232, 2021). "In addition, Septin4 can also inhibit the growth of hepatic stellate cells and negatively regulates the hepatic fibrosis through TLR4/TGF-β or PI3K/Akt pathway." (PMID 34230460, 2021). "In a future, we would like to determine the effects of partially silencing brain TLR4 on cardiac fibrosis, because %FS is often correlated with fibrosis and the release of catecholamines by the activation of SNS at the heart level is known to induce cardiac fibrosis." (PMID 23874864, 2013). "In summary, IGU inhibits the activation of macrophages and M1 polarization through inhibiting the TLR4/NF-κB pathway, thereby improving BLM-induced pulmonary inflammation and fibrosis in mice." (PMID 40181990, 2025). "In our experiments, IAP appears to rescue liver fibrosis only when TLR4 is present, suggesting that IAP protects the liver from fibrosis by potentially de-activating LPS, an important ligand in the TLR4 pathway." (PMID 33391458, 2021).
fibrosis (continued). "Dr. Varga research group has elegantly shown that TLR4 inhibition with TAK242 prevents and induces regression of experimental fibrosis in bleomycin-induced fibrosis and in TSK/+ mice." (PMID 30809542, 2019). "In this work, we show that the transcription of Tlr4 and Cd14 is upregulated in the liver of Sj-infected mice, and that suppression of TLR4 signaling by TAK242 decreases the extent of hepatic fibrosis induced by Sj infection." (PMID 29321784, 2017). "Absence of TLR4 gene attenuated chronic inflammation and colonic macrophages infiltration; intestinal fibrosis and collagen deposition were suppressed." (PMID 33199767, 2020).
liver cancer (49 papers, 2015 to 2025). An epithelial or non-epithelial malignant neoplasm that arises from the liver. "In our previous work, an anti-TLR4 antibody conjugated to ZW800-1C (TLR4- ZW800-1C) has been successful in detecting tumor-associated macrophages (TAMs) in liver cancer in a mouse model." (PMID 34944397, 2021). "Mice deficient in both TLR-4 and MyD88 have shown a significant decrease in the incidence and sizes of chemical-induced liver cancers, suggesting a strong relationship between TLR-4 signaling and hepatocarcinogenesis." (PMID 31540435, 2019). "For instance, IL-6/JAK/STAT3 signaling enhances bladder cancer cell growth and is linked to targeted kinase inhibitor resistance, while TLR4 activation facilitates inflammation-associated carcinogenesis and liver cancer metastasis through protein tyrosine kinase 2 (PTK2) induction." (PMID 41573719, 2025). "Although TLR4 antagonists show considerable promise for liver cancer therapy, clinical application still faces challenges." (PMID 41395459, 2025). "The TLR4 signaling pathway plays a critical regulatory role in liver cancer progression and represents a core molecular mechanism in the pathogenic effects of the gut-liver axis." (PMID 41395459, 2025). "In this study, we demonstrated that the autocrine function of RPLP2 in the extracellular domain promotes aerobic glycolysis in HCC cells by activating TLR4 and ultimately affects liver cancer cell proliferation." (PMID 38052785, 2023). "Using the 20 HCC tissues that were collected from HBV- and HCV-negative male HCC patients by the Taiwan Liver Cancer Network, the mRNA expression of TLR4, IL6 and CCL2 was determined using the quantitative polymerase chain reaction (qPCR)." (PMID 35955552, 2022). "Clinical studies have confirmed that the expression of TLR4 in HCC patients is closely related to liver cancer metastasis, early recurrence, and poor survival." (PMID 35965618, 2022). "M2 macrophages promote liver cancer cell metastasis via the toll like receptor 4 (TLR4) signaling pathway." (PMID 35110624, 2022). "The self-renewal of liver cancer stem cells (LCSCs) was characterized by increased expression of toll-like receptor 4 (TLR4), which led to CDDP, 5-FU, and DOX resistance in HCC." (PMID 36359776, 2022). "As a result, a large amount of LPS enters the liver through the portal vein and activates TLR4 expressed on KCs, hepatic stellate cells (HSCs), and liver cancer cells, promoting chronic hepatitis, cirrhosis, and even liver cancer." (PMID 35965618, 2022). "By screening the expression levels of TLR4 mRNA and protein in five different liver cancer cells, Huh7, PLC/PRF5 (PLC5), Hep3B, HepG2 and SK-Hep1, HepG2 and Hep3B were examined." (PMID 35955552, 2022). "For example, it is found in liver cancer that lipopolysaccharide (LPS) produced by the intestinal microbiota can activate toll-like receptor 4 (TLR4) to help patients with chronic liver disease progress to tumors." (PMID 34485534, 2021). "Knocking down β2-Spectrin in liver cancer cells can significantly increase the expression of TLR4 and enhance the self-renewal and tumorigenic activity of the cells." (PMID 33390831, 2021). "Previous reports demonstrate that AR promotes gender disparities in cancer 10, and TLR4 plays an important role in promoting liver cancer." (PMID 31956356, 2020). "In liver cancer we had shown that aberrant TLR-4-TRIF-NF-κB signalling mediated cancer cell debris-induced IL-1β production." (PMID 31588122, 2019). "In summary, our data indicate that TLR4 promotes liver cancer stem cells malignant progression by altering telomere length." (PMID 29602239, 2018). "Excessive TLR4 significantly promoted the colony formation ability of liver cancer stem cell (37.79 ± 3.29 vs 70.66 ± 7.53%, P = .0094 < .01)." (PMID 29602239, 2018). "This study elucidates a novel protection mechanism of TLR4 in liver cancer stem cells and suggests that TLR4 can be used as a novel therapeutic target for liver cancer." (PMID 29602239, 2018).
liver cancer (continued). "and (iii) Does TLR4 regulate a series of molecular events during the malignant growth of liver cancer stem cells?" (PMID 29602239, 2018). "In this study, we attempted to elucidate TLR4 functions during the malignant growth of liver cancer stem cells." (PMID 29602239, 2018). "The roles of TLR4 in liver cancer have been analyzed in several studies showing an inhibitory effect on HCC initiation in the DEN model and HCC promotion in a combined model of CCl4 and DEN." (PMID 27391331, 2016). "Curcumin has been reported to prevent liver cancer progression by inhibiting TLR4 signaling." (PMID 38612546, 2024). "Importantly, RPLP2 regulates aerobic glycolysis and liver cancer cell proliferation via TLR4-mediated HIF-1α translocation into the nucleus." (PMID 38052785, 2023). "Similarly, TLR4 knockout mice have been critical in understanding the oncogenic effect of gut microbiota in liver cancer." (PMID 36032113, 2022). "Human gut microbiota may produce LPS, which can activate Toll-like receptor 4 (TLR4), causing the development of liver cancer." (PMID 34948234, 2021). "Herein, we demonstrate that TLR4 promotes the malignant growth of liver cancer stem cells." (PMID 29602239, 2018). "The activation of TLR4 by LPS in liver cancer cell lines enhances their invasion ability and epithelial-mesenchymal transition and promotes the occurrence of HCC, suggesting that TLR4 may be a practical biological indicator of liver cancer metastasis and recurrence." (PMID 35965618, 2022). "Specifically, we investigated whether TLR4 promotes the malignant proliferation and growth of liver cancer stem cells in vitro and in vivo, and investigated its potential role in the malignant transformation of liver stem cells by analysing the cascade of TLR4‐HP1 (α, β and γ)‐telomere signalling." (PMID 29602239, 2018). "Finally, the function of TLR4 in liver cancer stem cells should be further explored." (PMID 29602239, 2018). "Although no experimental data pertaining to AGAP11 have been reported in the field of cancer, there is evidence to suggest that closely related genes, namely, LPL, MMP9, SGK1, TLR4, and FOS play certain roles in liver cancer through different mechanisms." (PMID 36726348, 2023). "Curcumin also inhibited liver cancer HepG2 cells‘ proliferation, invasion and metastasis through inhibiting heat shock protein 70 (HSP70)- toll-like receptor 4 (TLR4) signaling." (PMID 36009200, 2022). "PRRs, as lipopolysaccharides (LPS) produced by gut bacteria, can activate Toll-like receptor 4 (TLR4), thus inducing a series of inflammatory reactions to influence the development of liver cancer." (PMID 36429112, 2022). "Nanog is one of the core transcription factors found in pluripotent embryonic stem cells and an important marker/regulator of CSCs; Toll-like receptor 4 (TLR4) is upstream of Nanog and involved in the malignant transformation of liver cancer cells." (PMID 29156633, 2017). "Correspondingly, by employing gene signature analysis in online LIHC databases, we found that the mean expression of the gene set composed of KLF7, TLR4 and PTK2 was elevated in liver cancer tissues compared to normal livers, and further increased in liver cancer metastatic tissues." (PMID 37554278, 2023). "These different results regarding the correlation between TLR4 expression and STAT3 activation in liver cancer may be because of the different sample sizes of the two analyses." (PMID 32312954, 2020). "Therefore, targeting TLR4 or its homologous signals might be a potential molecular target for HCC treatment by regulating the proliferation and chemotherapy sensitivity of liver cancer cells." (PMID 35965618, 2022). "However, when protein phosphatase PP1 was expressed in the TLR4 overexpressing liver cancer stem cells, excessive TLR4 could significantly not alter the level of phosphorylation of HP1α, HP1β, HP1γ." (PMID 29602239, 2018).
liver cancer (continued). "However, when protein phosphatase PP1 was expressed in the TLR4 overexpressing liver cancer stem cells, excessive TLR4 could significantly not alter the length of telomere (2.427 ± 0.732 vs 2.123 ± 0.26, P = .193 > .05)." (PMID 29602239, 2018). "However, when protein phosphatase PP1 was expressed in the TLR4 overexpressing liver cancer stem cells, excessive TLR4 could significantly not alter the activity of telomerase (6.25 ± 1.37 vs 5.71 ± 1.91, P = .134 > 0.05)." (PMID 29602239, 2018).